CASC15 (cancer susceptibility 15)
Diseases named in the same sentence as CASC15 in open-access papers (continued):
Sharing a sentence is not in itself a finding about the gene and the disease.
ovarian carcinoma (5 papers, 2021 to 2023). A malignant neoplasm originating from the surface ovarian epithelium. "Our in vitro and in vivo results indicated an association between CASC15 transcript level and ovarian cancer metastasis." (PMID 35342355, 2022). "Our findings identified an epigenetic mechanism for CASC15-mediated cancer metastasis in ovarian cancer with implications in the diagnostic and therapeutic process." (PMID 35342355, 2022). "Collectively, the data indicated that higher expression of CASC15 was associated with poor survival in ovarian cancer." (PMID 35342355, 2022). "This study first described a miR-23b-3p/miR-24-3p-mediated positive feedback loop between CASC15 and SMAD3, which may reflect the underlying molecular mechanism of CASC15's oncogenic function in ovarian cancer." (PMID 35342355, 2022). "Cancer Susceptibility Candidate 15 (CASC15), which is a newly identified long noncoding RNA crucial for epigenetic regulation in human tumors, was found to be associated with poor prognosis of the patients with ovarian cancer by utilizing The Cancer Genome Atlas and Gene Expression Omnibus database." (PMID 35342355, 2022). "Previous studies have suggested that lncRNA CASC15 exerts tumor-promoting function in cervical 17 and breast 18 cancer, which is prominently influenced by female hormones resembling ovarian cancer." (PMID 35342355, 2022). "In this context, our results described a positive feedback loop of CASC15-SMAD3 in which CASC15 promoted the ovarian cancer EMT program and metastasis by increasing SMAD3 expression; in turn, SMAD3 stimulated the promoter activity of lncRNA CASC15." (PMID 35342355, 2022). "The CASC15 expression data and corresponding clinical data of ovarian cancer were downloaded from the cancer genome atlas (TCGA) and gene expression omnibus (GEO) database." (PMID 35342355, 2022). "CASC15 promoted metastasis of ovarian cancer via the EMT progression partly through interaction with the miR-23b cluster." (PMID 35342355, 2022). "We cannot exclude the possibility that lncRNA CASC15 promoted ovarian cancer EMT progress and metastasis through means other than the miR-23b-3p/miR-24-3p/SMAD3 pathway." (PMID 35342355, 2022). "In the present study, a series of experiments were performed to investigate the biological mechanism by which CASC15 exerted its function in ovarian cancer EMT and metastasis progression." (PMID 35342355, 2022). "Combined with basic data, our research indicated that CASC15 plays a tumor promoter role in ovarian cancer." (PMID 35342355, 2022). "Using the Kaplan-Meier survival analysis in the GEO dataset GSE9891 29, GSE26193 30, we found that ovarian cancer patients with high CASC15 expression had worse overall survival (OS) than those with low CASC15 expression." (PMID 35342355, 2022). "The low expression of CASC15 was closely associated with shorter overall survival (OS) and progression-free survival (PFS) of ovarian cancer patients." (PMID 35887085, 2022). "In conclusion, results obtained in this mouse model strongly supported the role of CASC15 as a metastatic promoter in ovarian cancer." (PMID 35342355, 2022). "Therefore, further research is urgently required to explore the functional role and latent molecular mechanism of CASC15 in the progression of ovarian cancer." (PMID 35342355, 2022). "Therefore, the purpose of this paper was to explore the functional role and latent molecular mechanism of CASC15 in the progression of ovarian cancer." (PMID 35342355, 2022). "CASC15 possessed a significant effect on the EMT program and metastasis in ovarian cancer, but the specific mechanism of CASC15 promoting EMT process remains unclear." (PMID 35342355, 2022). "In vitro and in vivo experiments validated CASC15 as an oncogenic lncRNA in ovarian cancer, which could enhance metastasis through TGF-β-induced epithelial-mesenchymal transition progress." (PMID 35342355, 2022).
ovarian carcinoma (continued). "We found that miR-23b-3p and miR-24-3p could additively suppress cancer metastasis through EMT in ovarian cancer cells independently of CASC15." (PMID 35342355, 2022). "We further evaluated whether CASC15 affected the migration and invasion of ovarian cancer cell in vitro." (PMID 35342355, 2022). "Our study identified an oncogenic role for lncRNA CASC15 in ovarian cancer." (PMID 35342355, 2022). "LncRNA CASC15 was verified to function as an unfavourable predictor for ovarian cancer." (PMID 33834618, 2021). "Four ovarian cancer cell lines were used in our study, including SKOV3, ES-2 with high expression of CASC15; and A2780, OVCAR-3 with low expression of CASC15." (PMID 35342355, 2022). "Since CASC15 was upregulated via TGF-β1, we tried to detect whether CASC15 regulated the EMT program in ovarian cancer." (PMID 35342355, 2022). "Nevertheless, previously published studies on the effect of lncRNA CASC15 in ovarian cancer 26, 27 are not consistent." (PMID 35342355, 2022). "Taken together, the present findings of our study suggested that a double-negative, namely, positive, regulatory circuit among CASC15 and SMAD3 may underlie CASC15-mediated ovarian cancer cell EMT and metastasis induction." (PMID 35342355, 2022). "Notably, our study found that CASC15 was a TGF-β downstream molecule and involved in the TGF-β/SMAD3 pathway in ovarian cancer: CASC15 was upregulated by TGF-β1, and then increased the expression of SMAD3 via serving as a ceRNA to facilitate cell migration and invasion in ovarian cancer." (PMID 35342355, 2022).
acute leukemia (4 papers, 2017 to 2021). A clonal (malignant) hematopoietic disorder with an acute onset, affecting the bone marrow and the peripheral blood. "Previous study has found that SOX4 expression is upregulated by a lncRNA CASC15 and promotes cell proliferation in acute leukemia." (PMID 32090981, 2020). "CASC15 expression was high in acute leukemia with RUNX1 translocations, and its expression in cells led to increased apoptosis and decreased engraftment in the hematopoietic system." (PMID 28724437, 2017). "In this study, we sought to delineate the function of CASC15 in acute leukemia." (PMID 28724437, 2017).
colorectal cancer (4 papers, 2019 to 2023). A primary or metastatic malignant neoplasm that affects the colon or rectum. "MSH6 coexpressed with two DElncRNAs (LOC105374879 and CASC15) and BCL2 coexpressed with B3GALT5‐AS1 were significantly enriched in the colorectal cancer signaling pathway." (PMID 31116002, 2019). "The overexpression of Lgr5 in the colorectal cancer cells occurs due to up or downregulation of several noncoding RNAs, such as CASC15 miR-4310 or miR-23a, as a consequence of activation of PI3K/Akt signaling pathway." (PMID 32671503, 2020).
hepatocellular carcinoma (4 papers, 2020 to 2024). A malignant tumor that arises from hepatocytes. "Meanwhile, cancer susceptibility candidate 15 (CASC15) promotescell EMT and facilitates malignancy of hepatocellular carcinoma cells via miR-33asponging." (PMID 35129574, 2022).
tongue squamous cell carcinoma (4 papers, 2019 to 2024). A squamous cell carcinoma that arises from the tongue. "In tongue squamous cell carcinoma, miR-33a-5p expression was significantly underexpressed, and CASC15 can directly target miR-33a-5p to promote the growth of tongue squamous cell carcinoma cells." (PMID 34426559, 2021). "The involvement of lncRNA CASC15 in several types of cancers has been reported, while its role in tongue squamous cell carcinoma (TSCC) is unknown." (PMID 31665008, 2019).
Astigmatism (3 papers, 2015 to 2025). A type of refraction error associated with abnormal curvatures on the anterior and/or posterior surface of the cornea. "SNPs near other loci, including RPS6KC1 rs12144639, ZC3H11B rs7525202, TRAF3IP1 rs77008212, and CASC15 rs4712652, were nominally associated with various types and components of astigmatism, as well as CR." (PMID 41320768, 2025).
breast carcinoma (3 papers, 2014 to 2025). "For instance, lncRNA CASC15 sustains breast cancer stemness through the miR-654-5p/MEF2D axis, while HAGLROS promotes tumor evolution via the miR-135b-3p/COL10A1 pathway and exosome-mediated macrophage polarization." (PMID 41614739, 2025). "Cancer susceptibility candidate 15 (CASC15) is familiarly observed to participate in regulation of tumor proliferation, metastasis, and worsen survival probability of human cancer including CRC, cervical cancer, breast cancer and so on." (PMID 31442207, 2019).
cardiac hypertrophy (3 papers, 2020 to 2023). "Additionally, Ang II modulates the expression of several lncRNAs in myocardial hypertrophy, including SYNE1-AS1, lncRNA SNHG14, and lncRNA CASC15." (PMID 35703318, 2022).
cutaneous melanoma (3 papers, 2017 to 2020). A primary melanoma arising from atypical melanocytes in the skin. "Otherwise, the CASC15 isoform exerts oncogenic functions in the cutaneous melanoma progression." (PMID 32366932, 2020).
leiomyoma (3 papers, 2022 to 2024). A well-circumscribed benign smooth muscle neoplasm characterized by the presence of spindle cells with cigar-shaped nuclei, interlacing fascicles, and a whorled pattern. "PRL, the associated protein-coding gene of CASC15, is one of the most highly expressed genes in leiomyomas." (PMID 35641855, 2022). "Our own studies have shown that CASC15 is upregulated in leiomyomas." (PMID 39519092, 2024). "MED12 mutation-negative leiomyomas display copy number alterations in several other mediator complex subunits, such as MED18, MED8, CDK8, and the long non-coding RNA, RNA340 (CASC15)." (PMID 38279317, 2024). "Finally, CASC15 expression was upregulated in many cancers and a potential hotspot for chromosome alterations in MED12-mutation-negative leiomyomas." (PMID 35641855, 2022).
lung adenocarcinoma (3 papers, 2021 to 2023). A carcinoma that arises from the lung and is characterized by the presence of malignant glandular epithelial cells. "Furthermore, we examined the expression levels of CASC15 and related proteins in fresh samples from seven lung adenocarcinomas and three normal lung tissues." (PMID 33407675, 2021). "To validate this axis in clinical samples, we downloaded and analyzed the gene expression profiles of HIF1A, CASC15, SOX4, and CTNNB1 (β-catenin) in two lung adenocarcinoma cohorts from TCGA database." (PMID 33407675, 2021). "Thereinto, patients who highly expressed CASC15 and LINC01137 have a poor prognosis and are immunosuppressed; however, CRNDE and CYP1B1-AS1 exhibited lower expression levels in lung adenocarcinoma and were closely related to the immunosuppressive microenvironment." (PMID 37637063, 2023).
cervical cancer (2 papers, 2019 to 2020). A primary or metastatic malignant neoplasm involving the cervix. "To our best knowledge, we firstly demonstrated that CASC15 polymorphisms were interaction with cervical cancer susceptibility in Chinese women." (PMID 32329235, 2020). "We observed that rs12212674 of CASC15 improved cervical cancer risk (OR = 1.32, 95% CI = 1.02–1.72, p = .037) in the log‐additive model." (PMID 32329235, 2020). "Our study firstly showed that there is a potential interaction between CASC15 polymorphisms and cervical cancer susceptibility." (PMID 32329235, 2020). "Here, we recruited 494 cervical cancer cases and 504 unrelated controls to assess the relationship between CASC15 (OMIM# 616610) polymorphisms and cervical cancer susceptibility." (PMID 32329235, 2020). "In summary, the results revealed the role of CASC15 polymorphisms in cervical cancer sensibility among Chinese women." (PMID 32329235, 2020). "Our results revealed a potential interaction between CASC15 polymorphisms and cervical cancer susceptibility." (PMID 32329235, 2020). "We observed that CASC15 rs4712653 “TT” genotype was associated with the risk of cervical cancer in aged ≤51 people (p = .036)." (PMID 32329235, 2020). "The case‐control study indicated that rs12212674 of CASC15 polymorphisms was significantly associated with an increased risk of cervical cancer (p = .041)." (PMID 32329235, 2020). "In addition, the relationship between CASC15 polymorphisms and cervical cancer sensibility was examined in four genetic models." (PMID 32329235, 2020). "Besides, detail molecular mechanism studies to further explore the role of CASC15 variants in increasing cervical cancer risk were necessary to be performed." (PMID 32329235, 2020). "Thus, we investigated the relationship between CASC15 polymorphisms and cervical cancer risk in the Chinese women." (PMID 32329235, 2020). "The results provided important insights into lncRNA CASC15 function in the development of cervical cancer." (PMID 32329235, 2020). "To date, no studies have reported the correlation between lncRNA CASC15 polymorphisms and cervical cancer susceptibility in Chinese females." (PMID 32329235, 2020). "The results provided important insights into CASC15 function in the development of cervical cancer." (PMID 32329235, 2020). "However, no study revealed that the correlation between CASC15 polymorphisms and cervical cancer susceptibility in the Chinese Han women." (PMID 32329235, 2020).
chronic renal failure (2 papers, 2020 to 2021). "For instance, MALAT1 enhanced the HG-induced cartilage endplate cell apoptosis by the p38/MAPK signaling pathway and CASC15 promoted diabetes-induced chronic renal failure and podocyte apoptosis." (PMID 34553078, 2021). "Up-regulation of lncRNA CASC15 was observed in plasma derived from diabetic patients complicated with chronic renal failure, thus indicating the potential diagnosis value of CASC15 for chronic renal failure." (PMID 32752143, 2020).
diabetes (2 papers, 2021). "Others were associated to Type 2 diabetes (CASC15, LINC01127, NUTM2B-AS1) or diabetes renal injury in T1D (HOTAIRM1)." (PMID 35058920, 2021).
leukemia (2 papers, 2017 to 2018). A malignant (clonal) hematologic disorder, involving hematopoietic stem cells and characterized by the presence of primitive or atypical myeloid or lymphoid cells in the bone marrow and the blood. "It will be of interest to examine CASC15 in other leukemia subtypes with RUNX1 loss-of-function, and these experiments are the focus of future studies." (PMID 28724437, 2017). "Our findings represent the first characterization of this CASC15 in RUNX1-translocated leukemia, and point towards a mechanistic basis for its action." (PMID 28724437, 2017). "Here, we assess the roles of the lncRNA CASC15 in regulation of a chromosomally nearby gene, SOX4, and its function in RUNX1/AML translocated leukemia." (PMID 28724437, 2017).
acute myeloid leukemia (1 paper, 2017). Acute myeloid leukemia (AML) is a group of neoplasms arising from precursor cells committed to the myeloid cell-line differentiation. "We also quantified CASC15 expression in 48 bone marrow aspirates from pediatric acute myeloid leukemia (AML) that showed 4 different translocations." (PMID 28724437, 2017).
Alzheimer disease (1 paper, 2024). A progressive, neurodegenerative disease characterized by loss of function and death of nerve cells in several areas of the brain leading to loss of cognitive function such as memory and language. "Given the pivotal involvement of CASC15 in synaptic plasticity and the distinctive regulatory mechanisms of the CASC15‐FMR1‐NTF3 axis, CASC15 emerges as a promising biomarker for Alzheimer's disease and may even possess potential as a feasible therapeutic target." (PMID 39713210, 2024).
Cerebral ischemia (1 paper, 2024). Restriction of arterial blood supply to the brain associated with insufficient oxygenation to support the metabolic requirements of the tissue. "CASC15 promotes cerebral ischemia/reperfusion injury via miR-338-3p/ETS1 axis in acute IS64." (PMID 38653998, 2024).
diabetic nephropathy (1 paper, 2025). "Retraction of: Li H, Hao J, Yu W. LncRNA CASC15 inhibition relieves renal fibrosis in diabetic nephropathy through downregulating SP-A by sponging to miR-424." (PMID 41141932, 2025).
ependymoma (1 paper, 2023). A WHO grade II, slow growing tumor of children and young adults, usually located intraventricularly. "Therefore, we focused on comparing the overlapping clusters between normal and tumor and identified tumor-specific genes such as CASC15 and microRNA MIR99AHG in neuron-like ependymomas and RPS14 and RPS8 in glia-like ependymomas." (PMID 37095395, 2023).
esophageal squamous cell carcinoma (1 paper, 2024). Esophageal squamous cell carcinoma (ESCC) is a type of esophageal carcinoma (EC) that can affect any part of the esophagus, but is usually located in the upper or middle third. "Besides, the long noncoding RNA CASC15 has been observed to interact with FTO to regulate the progression of esophageal squamous cell carcinoma." (PMID 38508309, 2024).
head and neck cancer (1 paper, 2022). A primary or metastatic malignant neoplasm affecting the head and neck. "Analysis of TCGA dataset revealed the upregulation of CASC15 in head and neck cancer (0.79 vs. 0.3, LSCC is a type of head and neck cancer)." (PMID 35216636, 2022).
laryngeal squamous cell carcinoma (1 paper, 2022). A squamous cell carcinoma that arises from the larynx. "This study investigated the role of lncRNA CASC15 in laryngeal squamous cell carcinoma (LSCC)." (PMID 35216636, 2022).
lymph node metastasis (1 paper, 2023). "Comprehensive analysis indicated that the expression of LINC01600 was significantly associated with KRAS mutation and lymph node metastasis, and CASC15 and LINC01600 were significantly tended towards co-occurrence, which may be due to the similarity of genes co-expressed by these 2 lncRNAs." (PMID 37960753, 2023). "However, the associations between CASC15 and LINC01600 and other clinical features, including sex, age in diagnosis, tumor stage and lymph node metastasis, were observed." (PMID 37960753, 2023).
metastatic disease (1 paper, 2019). "In this same position, three SNPs, namely CASC15, CASC15-S, and CASC14, were identified by Genome-Wide Association Study (GWAS) and associated with metastatic disease, amplification of MYCN oncogene, and more advanced disease." (PMID 30791380, 2019).
Neonatal sepsis (1 paper, 2021). Systemic inflammatory response to infection in newborn babies. "The expression level of CASC15 was increased in neonatal sepsis patient group, while miR-144-3p expression was decreased." (PMID 34870560, 2021). "The highly expressed CASC15 is capable of distinguishing neonatal sepsis from neonatal pneumonia." (PMID 34870560, 2021).
Oral ulcer (1 paper, 2024). Erosion of the mucous mebrane of the mouth with local excavation of the surface, resulting from the sloughing of inflammatory necrotic tissue. "This upregulation of CASC15 effectively distinguishes OSCC patients from those with oral ulcers and healthy individuals." (PMID 39192980, 2024).
pneumonia (1 paper, 2021). An acute, acute and chronic, or chronic inflammation focally or diffusely affecting the lung parenchyma, caused by an infection in one or both of the lungs (by bacteria, viruses, fungi, or mycoplasma.). "In the current study, we did not further analyze the diagnostic value of CASC15 in sepsis, but preliminarily verified its ability to distinguish sepsis from pneumonia." (PMID 34870560, 2021).
renal cell carcinoma (1 paper, 2019). "MALAT1 in renal cell carcinoma (RCC) and CASC15 in GC induce EMT by decreasing the level of E-cadherin." (PMID 31575017, 2019).
Sepsis (1 paper, 2021). Sepsis is defined as life-threatening organ dysfunction caused by a dysregulated host response to infection. "At present, there are relatively few related studies on CASC15 and sepsis, while most of the studies on CASC15 focus on inflammation." (PMID 34870560, 2021).